STAT1 (signal transducer and activator of transcription 1)
Diseases named in the same sentence as STAT1 in open-access papers (continued):
Sharing a sentence is not in itself a finding about the gene and the disease.
breast cancer (continued). "It thus seems possible that STAT1 and IRF1 act in a common axis to suppress MIN and subsequently mammary tumor formation." (PMID 22185785, 2011). "We took as «baits» five bimodal genes reported as important breast cancer genetic markers - ERBB2, ESR1, PLAUR, FN1, and STAT1, and calculated the "close neighbor" gene groups that were synchronously expressed with each of them in the Sorlie295 set." (PMID 20158879, 2010). "Supershift analysis suggests that Stat1 and possibly other members of the STAT family of signalling factors, including Stat3, are activated in breast cancer tissues." (PMID 7710952, 1995). "It was shown that, in SKBR3 breast cancer cells, after 24-h treatment with IFN-γ, the STAT1 and phosphorylated STAT1 (p-STAT1) were dose dependently increased in the groups treated with different concentrations of IFN-γ compared with the control group with statistical significance (p < .05)." (PMID 40596738, 2025). "For example, when stimulated with EGF, PLSCR1 not only directly binds to the promoter of STAT1, but also enhances STAT3’s binding to the STAT1 promoter in breast cancer cells, leading to the transactivation of STAT1 and basal-like breast cancer (BLBC) progression." (PMID 40248364, 2025). "In breast cancer BMX overexpression promotes proliferation by upregulating the activity of downstream substrates Protease Activated Receptor 1 (PAR1), p21 Activated kinase 1 (PAK1), and Signal Transducer and Activator of Transcription 1 (STAT1;)." (PMID 41213918, 2025). "Though the Stat1-knockout, BLG-Cre; Kras(G12V), and NRL-PRL models develop HR+ mammary tumors that are sensitive to hormonal perturbations such as ovariectomy and fulvestrant treatment, they all are hindered in their utilization potential by their driver mutations." (PMID 38913216, 2024). "These include EMT (TWIST1, SNAIL1, RUNX1, RUNX2, HIF1, and NOTCH1), breast cancer maintenance (OCT4, SP1, GATA1, ATF1, FOXO3a, ELK1, VDR, and NRF1), pro-metastatic responses (SMAD2/3, HNF1a, GLI1, NANOG, YY1, MYB1, and AP1), and immune modulation (STAT1/3)." (PMID 38398186, 2024). "Moreover, STING expression was also positively correlated with the expression of the IFN‐I signaling genes ISG15, STAT1 and STAT2 in breast cancer MSCs." (PMID 38638003, 2024). "A previous study has identified that suggest that increased STAT1 signaling is important in endocrine resistance and that STAT inhibitors may represent potential therapies in endocrine-resistant breast cancer." (PMID 37187897, 2023). "Together, these findings indicate that down-regulation of PD-L1 N-linked glycosylation was connected to inhibition of STAT3 and STAT1 activation (noted in MCF-7 cells), and to reduced cell-autonomous and PD-1-induced tumor cell invasion and release of pro-tumorigenic factors in breast cancer cells." (PMID 37830552, 2023). "Next, we determined whether DVL2 binds to the promoter regions of genes involved in antigen presentation (HLA-A, HLA-C) and T-cell maintenance (STAT1, STAT6, TGFB1) in HER2-positive breast cancer cells." (PMID 36809986, 2023). "Connections between impaired IFN-γ signaling responsiveness via p-STAT1 in peripheral monocytes and tumor associated macrophage (TAM) infiltration in paired primary tumors have been noted in patients with non-metastatic breast cancer." (PMID 37741983, 2023). "Notably, a subset of IFN-regulated genes that constitute an IFN-related DNA damage signature (IRDS), which includes STAT1, provides protection against DNA damage sensed by cGAS-STING in breast cancer cell lines." (PMID 37349798, 2023). "Our findings on the roles of STAT3 and STAT1 in mediating PD-L1 activities in breast cancer indicate that STAT3 and STAT1 cannot act independently from each other, and suggest that intersections exist between these two transcription factors in mediating PD-L1-induced effects." (PMID 37830552, 2023).
breast cancer (continued). "Altogether, these studies using phosphoflow cytometry reveal that cancer patients, including those with melanoma and breast cancer, exhibit defects in IFN-α and IFN-γ signaling in their peripheral blood lymphocytes, which is evidenced by reduced activation of p-STAT1." (PMID 37741983, 2023). "In examining the upstream regulatory mechanism of TINCR in breast cancer, we found that IFN-γ stimulation can activate downstream STAT1 signaling and that STAT1 migrates to the nucleus to promote the transcription of TINCR, thus regulating the expression of downstream miR-199a-5p, USP20, and PD-L1." (PMID 36725842, 2023). "Here, we demonstrate that the ability of PD-L1 to induce cell-autonomous- and PD-1-induced effects is mediated through STAT3 and STAT1 activation, leading to increased tumor cell growth, CXCL8 release and cancer cell invasion in luminal A and TNBC breast cancer cells." (PMID 37830552, 2023). "Interestingly, in basal-like breast cancer (BLBC) nuclear PLSCR1 was found to interact with STAT3 and bind to contiguous sites at the STAT1 promoter region, resulting in STAT1 transcriptional activation." (PMID 35650588, 2022). "To further confirm the selectivity of LLL12B in breast cancer cells, we tested its effects on the phosphorylation of STAT3, STAT1, or ERK following the stimulation with IL-6, IFN-γ, or EGF in the T47D breast cancer cells, which express lower basal levels of P-STAT3, and in the MDA-MB-231 TNBC cells." (PMID 36009550, 2022). "Moreover, the PPI network uncovered the crucial roles of numerous proteins (e.g., FOXP3, STAT1, STAT4, FOXP3, JUN, and CD3D) in breast cancer." (PMID 36704358, 2022). "Taken together, these results suggest that miR-155 in breast cancer cells enhances CXCL9/10/11 expression by suppressing SOCS1 expression and tilting the p-STAT1/p-STAT3 ratio, leading to the recruitment of effective T cells to the tumor site and subsequently an improved antitumor immune response." (PMID 35925680, 2022). "Mice lacking functional STAT1, a transcription factor utilized by all three classes of interferons, develop breast cancer spontaneously." (PMID 35681772, 2022). "The study reports that high expression levels of miR-155 in breast cancer cells downregulated suppressor of cytokine signaling 1 (SOCS1), increased the phosphorylated STAT1 (pSTAT1)/pSTAT3 ratio, and thereby stimulated chemoattractants for tumor infiltration of effector T cells." (PMID 36189796, 2022). "In addition, STAT1 and ERα directly interact and regulate a key interferon-stimulated gene, IFITM1, in AI-resistant breast cancer cells." (PMID 34680281, 2021). "We selected a low concentration of IFNγ (1 ng/mL) that induces STAT1 transcriptional responses (β2M, Tap1) but does not impair breast cancer cell growth." (PMID 34083537, 2021). "Besides, researchers analyzed the gene expression data of invasive breast cancer tissues and proved that the JAK/STAT1 pathway activated by IFNγ was positively correlated with PD-L1 expression." (PMID 34365463, 2021). "To determine whether this connection could be observed in human breast tumors, we probed the TCGA basal-like breast cancer data set for a previously published Ras/MAPK activity score and a STAT1 activation score." (PMID 33062958, 2020). "In contrast, heparin inhibited the stimulatory effect of IFN-γ on the production of CXCL9 and CXCL10 by human breast cancer cells by inhibiting cellular IFN-γ binding and modulating the IFN-γ-induced signal transducer and activator of transcription 1 (STAT1) phosphorylation." (PMID 32296423, 2020). "Collectively our findings suggested a novel role for SPHK1 in attenuating STAT1-mediated IFN signaling, and therapies targeting this signaling axis may be beneficial to breast cancer patients." (PMID 32260399, 2020).
breast cancer (continued). "Our study has also established that phosphorylation of PLSCR1 Tyr 69/74 plays an instrumental role in the proliferation and stemness of breast cancer cells by promoting its nuclear translocation, interaction with STAT3 and subsequent binding to the STAT1 promoter." (PMID 32292520, 2020). "The observed reduction in STAT1 expression suggests a feedback regulatory mechanism of pSTAT1 on its own promoter, already documented, as well as an EGFR/HER2-dependent regulation as previously shown in glioblastoma and breast cancer cell lines." (PMID 32642677, 2020). "Initially, we evaluated the expression of IFN-signaling proteins (STAT1 (Y701), STAT1, STAT2, IRF9) and IFN-stimulated proteins that induce an antiviral state (OAS1 and MxA) in MCF7/pS, MCF7/pR, 231/pS and 231/pR breast cancer cells in the absence or presence of palbociclib." (PMID 31100952, 2019). "Our results indicate that individual STATs, except STAT1 and STAT2, may act as a favorable prognostic biomarker in breast cancer." (PMID 29326301, 2018). "Silencing of STING after mafosfamide treatment of breast cancer cells delayed the appearance of growing colonies of surviving cells, showing that the STING/IFN/STAT1 pathway acts as a cellular mechanism of cancer cell survival and re-growth after the genotoxic stress of chemotherapy." (PMID 30186768, 2018). "Due to the multifaceted roles of STAT3 and opposing roles between this protein and STAT1 along with previous reports that C12-HSL can downmodulate STAT3 in breast carcinoma cells, we investigated the effect of C12-HSL on changes in both gene and protein expression of these molecules in PCa cells." (PMID 29854771, 2018). "Moreover, genomic analysis of mammary tumors arising in the 129:Stat1−/− mouse established they almost always harbored a truncating exon 10 mutation of the prolactin receptor (PRLR) that was tumorigenic when heterozygously expressed in embryonic fibroblasts lacking Stat1 but overexpressing Jak2." (PMID 28865492, 2017). "Given these different growth patterns, we also examined how perturbation in phosphotyrosine-dependent ShcA signalling impacts the STAT1 and STAT3 activation status of mammary tumours that display immune surveillance (MT/Shc2F/2F) versus suppression (MT/ShcA+/+ and MT/Shc313F/313F) phenotypes." (PMID 28276425, 2017). "Across the breast cancer cell line panel, including one radio-resistant glioblastoma cell line (U-87) used for comparison, the TNBC cell lines MDA-MB-231 and HCC1806 had the highest basal and post-IR treatment levels of p-STAT1 protein." (PMID 28279982, 2017). "A DNA microarray analysis identified that RNA interference of CD24, the breast cancer stem cells (BCSC) marker, could increase the expression of STAT1, which enhanced invasiveness and superior tumorigenicity." (PMID 28422733, 2017). "Surprisingly, STAT1 deletion in MT/ShcA+/+ (STAT3High) mammary tumours significantly impaired tumour onset in CD8+/+ mice (∼40% penetrance) but was dispensable for tumour initiation in CD8−/− animals, suggesting that STAT1 contributes to the establishment of immune suppression in STAT3High tumours." (PMID 28276425, 2017). "While no obvious changes were observed in the phosphorylation levels of STAT1 and STAT5, a conclusion may be safely conducted that PMM-172 primarily suppressed STAT3 activation in STAT3-dependent breast cancer cells." (PMID 28588262, 2017). "KO of Stat1 in other mouse strains and using other targeting approaches does not lead to spontaneous primary mammary tumors." (PMID 28865492, 2017). "Further, upregulation of ISGs like STAT1, STAT2, or IRF9 is known to promote cancer resistance to chemotherapy and radiotherapy as demonstrated in human head and neck squamous cell carcinoma and breast cancer." (PMID 27533247, 2016).
breast cancer (continued). "Despite the fact that several experimental studies suggest that STAT1 and STAT3 play a critical role in breast cancer tumorigenesis, the prognostic value of these proteins in patients with breast cancer remains unclear." (PMID 27769057, 2016). "Since breast cancer cells have been shown to express IFN receptors, these observations suggested that activation of the IFN/STAT1 pathway might be induced by an autocrine/paracrine mechanism." (PMID 27791205, 2016). "Expression levels of STAT1 and STAT3 transcript were then analyzed in 550 breast cancers from publicly available gene expression datasets (GSE2990, GSE12093, GSE6532), and protein expression was measured in an independent cohort of 546 primary breast cancers." (PMID 24728078, 2014). "It is feasible that STAT1 and STAT3 may have differing roles in different breast cancer subgroups dependent on whether they are hormonally or growth factor-driven." (PMID 24728078, 2014). "To evaluate the roles of STAT1 and STAT3 further, we used cell line models to study functional responses in endocrine sensitive and resistant breast cancer cells and then primary breast cancer samples to evaluate the associations between expression levels and clinical outcome." (PMID 24728078, 2014). "Microarray analysis of Ifn-γ/Jak/Stat1 effector genes, such as Gbp1 and Gbp5, have grouped the pathway with estrogen receptor negative (ER-) and triple-negative (ER−/PR/Her2-) breast cancers." (PMID 23520493, 2013). "Phenotypic marker analyses demonstrate that STAT1-/- mammary tumors arise from luminal epithelial cells, but not myoepithelial cells." (PMID 22264274, 2012). "STAT1-/- mice that were sterilely re-derived and housed exclusively in a commercial gnotobiotic facility also developed mammary tumors, a result suggesting that the disease was not of infectious origin." (PMID 22264274, 2012). "Herein, we show that a subset of human breast cancers display reduced STAT1 expression and that mice lacking STAT1 surprisingly develop ERα+/PR+ mammary tumors." (PMID 22264274, 2012). "In contrast, SSM1 did not require ovarian hormones for in vivo growth, revealing that not all STAT1-/- mammary tumor cells display hormone dependency." (PMID 22264274, 2012). "All primary STAT1-/- mammary tumors examined, regardless of parity, showed similar histopathological characteristics and patterns of hormone receptor expression." (PMID 22264274, 2012). "Interestingly, several of the elements identified in our computational analysis are bound by transcription factors such as STAT1, STAT3, STAT5, ETS1, PAX and E2F, which play important roles in mammary function and in breast cancer." (PMID 21655091, 2011). "Our transplantation studies revealed that the absence of STAT1 from the immune system significantly enhances tumor incidence and shortens the latency of mammary tumor formation." (PMID 22185785, 2011). "Sunitinib or Sorafenib activates the IFNγ/STAT1 pathway, which improve the expression of MHC I. When combined with whole-tumor-antigen-loaded nanovaccines, these nanovesicle formulations elicited a synergistic antitumor effect in both breast cancer and melanoma mouse models." (PMID 41019037, 2025). "STAT1 plays a key role in regulating the effect of chemotherapy; TYMP is considered to be a potential prognostic marker for ovarian cancer and breast cancer; GBP5, as an immune response regulator, can affect tumor progression; and PSME2 is closely related to the progression of various tumors." (PMID 40259929, 2025). "Additionally, in breast cancer, there’s evidence of alteration in metabolism to a glycolytic type through the transforming growth factor-β (TGF-β)-STAT1-succinate dehydrogenase (SDH)-hypoxia-inducible factor 1α (HIF1α) pathway, both in ex vivo and in vivo murine models." (PMID 38541208, 2024).
breast cancer (continued). "Considering that STAT1 signaling activation plays an important role in tumor cell metastasis via cell adhesion molecules induction, it is highly plausible that MFGE8-L, but not MFGE8-S, impeded breast cancer cell motility and invasive capability in a STAT1-dependent manner." (PMID 38995840, 2024). "Interestingly, microarray analysis demonstrated that STAT1 is co-expressed with ESCO2 and may regulate its transcription in breast cancer." (PMID 37968576, 2023). "The interactions of the mTOR cascade with STAT-mediated signaling (e.g., in immunity), and the roles attributed to STAT3 and STAT1 in promoting PD-L1 expression, have led us to inquire in depth about the potential involvement of STAT3 and STAT1 in PD-L1-mediated effects in breast cancer cells." (PMID 37830552, 2023). "Unlike breast cancer, we found STAT1 activity was suppressed in the OSCC cells." (PMID 35249111, 2022). "ISGylation of STAT1 and STAT2 mediate clustering and nuclear relocalization of STAT1 and STAT2 within IFN-induced PML bodies and synergistically promotes the production of chemokine-receptor ligands to attract cytotoxic T cells, thereby suppressing murine breast cancer growth and metastasis." (PMID 36319753, 2022). "Indeed, STAT1 signaling downregulates NQO1, a key ROS scavenger, in many breast cancer models." (PMID 34083537, 2021). "Mice lacking STAT1 spontaneously develop mammary carcinomas." (PMID 34830789, 2021). "Indeed, STAT1 inhibitors SOCS1 and SHP1/2 (component of PTPs) are also commonly hyperactivated in breast cancer, and elevated expression of PIAS1 has been observed in prostate and breast cancers." (PMID 31658669, 2019). "One of STAT1-target gene, ISG15, a ubiquitin-like protein, is also involved in the regulation of the expression of stemness-related genes, cell growth, cell migration, and tumorigenicity in pancreatic ductal adenocarcinoma, hepatocellular carcinoma and breast cancers." (PMID 30709063, 2019). "Ablation of STAT1 in CAF may decrease cancer cell proliferation and reduce α-SMA+ reactive fibroblasts and ductal carcinoma in situ (DCIS)-like lesions in a mouse model of early breast cancer progression." (PMID 30871158, 2019). "Interestingly, CXCL10, IRF1, and STAT1, shown to be expressed in breast cancers of patients who did not relapse, were also induced by EAD." (PMID 30486871, 2018). "Mice lacking both Rag2 and Stat1 developed an excess of colon cancer and breast carcinomas." (PMID 29881389, 2018). "Indeed, we could identify human breast tumours that coordinately increase STAT1- and STAT3-driven transcriptional responses in human breast cancers." (PMID 28276425, 2017). "We first identified breast cancer cell lines mimicking in vitro the drug-induced activation of the IFN/STAT1 signature observed in vivo, then we used these models to decipher both the upstream mechanisms and downstream consequences of this IFN/STAT1 fingerprint." (PMID 27791205, 2016). "However, neither the actual mechanisms by which chemotherapy triggered the IFN/STAT1 pathway in these breast cancer PDXs nor the actual contribution of the ISG fingerprint to the tumor response were elucidated." (PMID 27791205, 2016). "Moreover, signaling pathways such as mitogen activated protein kinases (MAPK) and PI3K/Akt that are frequently activated in breast cancer cells modulate expression of IRF1 and STAT1, further impacting the levels of IFN-γ inducible CIITA and subsequent HLA-II expression on tumor cells." (PMID 24475282, 2014). "Since downregulation of STAT1 expression is restricted to the neoplastic epithelial cells but not to the surrounding stromal cells, somatic silencing of STAT1 transcription may occur preferentially in the breast cancer cells." (PMID 22264274, 2012).